CRP (C-reactive protein)
Diseases named in the same sentence as CRP in open-access papers (continued):
Sharing a sentence is not in itself a finding about the gene and the disease.
acute coronary syndrome (continued). "Concomitantly, statins reduce circulating levels of inflammatory markers such as C-reactive protein (CRP), leading to a prognostic benefit both in apparently healthy patients and in patients with acute coronary syndrome (ACS)." (PMID 40149635, 2025). "These interpretations are consistent with the temporal arrangement of measurements (baseline lipids vs. post-procedure CRP) and the exclusion of patients with acute coronary syndrome from the study." (PMID 40990749, 2025). "One analysis showed preferential results for DES implantation compared with BMS in ST-segment elevation acute coronary syndrome patients in relation to ST in the presence of elevated high-sensitive CRP." (PMID 41091145, 2025). "There is clinical evidence supporting the prognostic value of CRP and IL-6 in acute coronary syndrome; however, the relevance of IL-1β and TNF-α as prognostic markers in this context remains uncertain." (PMID 40168324, 2025). "Second, included studies included patients with a variety of PCI indications, including acute coronary syndromes, especially acute MIs, which is perhaps one of the most important sources of heterogeneity in CRP levels." (PMID 40309624, 2025). "Reductions in HF-related events and high-sensitivity-CRP levels were observed in the first 14 days after the acute coronary syndrome." (PMID 40428204, 2025). "Conversely, low levels of fet-A, coupled with increased C-reactive protein (CRP) levels, have been associated with an increased risk of CV-related mortality in patients experiencing acute coronary syndrome." (PMID 39337398, 2024). "C-reactive protein (CRP) is considered a cardiovascular risk factor since its elevated levels have been associated with adverse cardiovascular outcomes, like acute coronary syndrome (ACS), as well as in the initiation and development of atherosclerotic plaque." (PMID 39062000, 2024). "Among patients presenting with acute coronary syndrome and undergoing coronary interventions, pre-procedural C-reactive protein is an independent predictor of readmission to the hospital within 6 months of hospital discharge." (PMID 39197405, 2024). "Among these, C-Reactive Protein (CRP) and Interleukin-6 (IL-6) are both significantly upregulated in acute coronary syndrome." (PMID 38140053, 2023). "In patients with acute coronary syndrome, serum levels of IL‐39 were also significantly increased and showed a positive correlation with high‐sensitivity C‐reactive protein (CRP)." (PMID 36757903, 2023). "There have also been small RCTs exploring the impact of colchicine on high sensitivity c-reactive protein (hs-CRP) in patients after an acute coronary syndrome, with mixed results." (PMID 38089775, 2023). "pEVs have been shown to correlate with the size of the myocardium at risk after an acute coronary syndrome (ACS) and to act as biomarkers of vascular inflammation, perhaps because they contain some proinflammatory isoforms of C-reactive protein (CRP)." (PMID 36901997, 2023). "In this study, we investigated the relationship between long-term mortality and the CRP/albumin ratio in patients with acute coronary syndromes (ACS)." (PMID 38022331, 2023). "The more elevated the CRP levels, the greater the chances for severe acute coronary syndrome, ventricular remodelling, lower EF, cardiac rupture, HF and cardiac death." (PMID 38137807, 2023). "Evidence suggests that there is a positive correlation between SUA and serum CRP levels in healthy populations, patients with acute coronary syndrome, and CKD patients undergoing peritoneal dialysis." (PMID 35192651, 2022). "Increased concentrations of C-reactive protein (CRP), amyloid A, or interleukin 6 (IL-6) were observed in a significant percentage in patients with acute coronary syndromes." (PMID 36071866, 2022).
acute coronary syndrome (continued). "In early observational studies of general and acute coronary syndrome (ACS) populations, high levels of CRP were found to represent a poorer prognosis, perhaps underlying a previously unrecognised inflammatory process relating to atherosclerosis." (PMID 35192610, 2022). "The same was true for the high-sensitivity CRP, non-acute coronary syndrome (ACS), <12 months duration, and clear measurement subgroups." (PMID 35966518, 2022). "From 917 patients with acute coronary syndrome, 574 had low inflammation (CRP < 2 mg/L) and 343 had persistent inflammation (CRP ≥ 2 mg/L)." (PMID 33803115, 2021). "In epidemiological studies, PCSK9 is positively correlated with inflammatory markers, such as CRP, white blood cell count and fibrinogenin patients with acute coronary syndromes." (PMID 34692791, 2021). "Therefore, the main objective of this study is to analyse and compare the effects of an adapted tennis CRP and those of a classical bicycle ergometer-based CRP on the type of motivation towards sporting practice and the HRQoL of low-risk patients who have suffered acute coronary syndrome (ACS)." (PMID 34501797, 2021). "It has been reported that D-dimer and C-reactive protein (CRP) both provide prognostic information in patients with acute coronary syndromes, probably based on the close relation between inflammation and ischaemic heart disease." (PMID 33920725, 2021). "The REVERSAL and PROVE-IT trials saw high-intensity statin intervention mediating a significant reduction in C-reactive protein (CRP) as well as endpoints in plaque progression and the onset of acute coronary syndrome (ACS)." (PMID 34068406, 2021). "CRP is a standard for highlighting the inflammatory process in acute coronary syndrome compared with the relatively recent inflammatory markers introduced into the clinic (interleukin [IL]-1β, IL-6 and stromal-derived factor 1α [SDF-α])." (PMID 34180324, 2021). "A growing set of clinical evidence suggests that neutrophil-to-lymphocyte ratio (NLR), CRP, albumin, and lymphocyte are easily accessible and cheap markers to assess inflammation, especially in acute coronary syndromes." (PMID 33094574, 2020). "In particular, the Aggrastat-to-Zocor (A to Z) trial demonstrated that the clinical outcome of patients with acute coronary syndromes significantly improves when the hs-CRP levels are lowered below 2 mg/L." (PMID 33081810, 2020). "The Pravastatin or Atorvastatin Evaluation and Infection Therapy (PROVE-IT) trial enrolled 3,745 patients with acute coronary syndrome to undergo moderate or high-dose statin therapy and concluded that patients with lower CRP had lower cardiovascular events." (PMID 32550081, 2020). "Along with other inflammatory markers, namely interleukin 6 (IL-6) and C-reactive protein (CRP), the level of hGIIA sharply increases during the first four days after acute coronary syndrome (ACS)." (PMID 32998383, 2020). "The most common finding was down-regulation of systemic inflammation in HF and acute coronary syndrome identified through measurement of C-reactive protein (CRP) and other pro-inflammatory factors." (PMID 31083399, 2019). "Several biomarkers have been investigated for the diagnosis and risk stratification of acute coronary syndrome (ACS): cardiac troponin, creatine kinase-myocardial band and high sensitive C-reactive protein (hs-CRP)." (PMID 31399624, 2019). "The aim of this study is to compare the effects of rosuvastatin and atorvastatin in lowering hs-CRP levels in statin-naive patients admitted with acute coronary syndrome." (PMID 31423377, 2019). "The aim of this study is to compare the effects of rosuvastatin and atorvastatin in lowering hs-CRP levels in statin-naive patients admitted with acute coronary syndrome (ACS)." (PMID 31423377, 2019). "In vitro findings suggest that CRP interacts with monocytes to enhance inflammation in acute coronary syndrome." (PMID 30192769, 2018).
acute coronary syndrome (continued). "Acute coronary syndrome patients have elevated inflammation as a result of increased CRP in coronary circulation." (PMID 29644527, 2018). "Elevated circulating inflammatory markers, particularly C-reactive protein (CRP), can predict the risk of atherosclerotic cardiovascular events and poor outcomes in acute coronary syndromes." (PMID 30274193, 2018). "In multiple other conditions linked to an activated inflammatory response, such as acute coronary syndrome, chronic urticaria, or pancreatitis, correlations exist between high MMP-9 levels and C-reactive protein (CRP)." (PMID 29929486, 2018). "A randomized controlled trial where 100 mg of aspirin was given for acute coronary syndrome showed decrease in the level of both CRP and TNF-α24." (PMID 29707192, 2017). "Studies also supported that CRP had direct proinflammatory effect and was an independent risk factor in a variety of cardiovascular diseases and might be used as a biomarker to predicate the risk of cardiovascular disease and to predicate the long-term outcome of acute coronary syndrome." (PMID 28115972, 2017). "Circulating inflammatory biomarkers such as C-reactive proteins (CRP) and certain cytokines are also elevated in acute coronary syndrome, which reflect the extent of myocardial necrosis and ischemia/reperfusion damage." (PMID 24736319, 2014). "Longitudinal studies have demonstrated that Interleukin 6 (IL-6) is a better predictor of CHF after acute coronary syndrome (ACS) than C-reactive protein (CRP), and that it is also an independent predictor of cardiovascular mortality." (PMID 25100442, 2014). "Our previous clinical studies showed that a persistent and enhanced inflammatory responsiveness to pro-inflammatory stimulators, such as C-reactive protein, are involved in the pathogenesis of acute coronary syndrome." (PMID 25519174, 2014). "The CRP level in the four groups was 5.6 mg/L, 4.7 mg/L, 3.0 mg/L, and 2.5 mg/L, respectively, and compared to control group, the acute coronary syndrome was significantly higher." (PMID 25762441, 2014). "Plasma CRP level increases significantly during acute phase of KD, which is an independent predictor for acute coronary syndromes." (PMID 25093412, 2014). "Several other biomarkers, e.g. C-reactive protein (CRP) and interleukin 6 (IL-6), have been identified also to indicate acute coronary syndrome (ACS)." (PMID 24313641, 2013). "The risk predictors of acute coronary syndrome include serum biomarkers (troponin I, BNP and CRP), ECG analysis and imaging techniques." (PMID 23596482, 2013). "Statins were also shown to confer rapid benefits in patients with acute coronary syndrome by blocking pathologic factors such as CRP, tissue factor, IL-1, IL-6, and other pro-inflammatory cytokines." (PMID 23950953, 2013). "In clinical studies, elevated plasma MIF levels in patients with acute coronary syndrome also correlated with increased inflammatory markers such as C-reactive protein (CRP) and IL-6." (PMID 24098445, 2013). "In patients with acute coronary syndrome, an elevated CRP level has also been shown to be a good predictor of morbidity and mortality." (PMID 23950953, 2013). "The objective of our study is to verify if PON1 55 polymorphism is associated with risk of acute coronary syndrome (ACS) and with biochemical myocardial ischemia markers, such as troponin I, creatine kinase (CK)-MB, myoglobin, and C-reactive protein." (PMID 22536511, 2012). "The CRP assay was not a high sensitivity one, but this fact is not expected to influence our results, as all patients are suffering from an acute coronary syndrome and are, therefore, expected to exhibit elevated values of CRP." (PMID 19503842, 2009). "In particular, pro-inflammatory cytokines and acute phase reactants including C-reactive protein (CRP), have been used as biomarkers and predictors for acute coronary syndromes (ACS)." (PMID 18335048, 2008).
acute coronary syndrome (continued). "Furthermore, the increased level of C-reactive protein (CRP) is now widely recognized as being an independent risk factor for a higher incidence of non-fatal and fatal coronary events in patients with chronic ischemic heart disease and acute coronary syndromes." (PMID 15790413, 2005). "At baseline, a high incidence of the inflammatory syndrome can be observed in more than half of the patients with acute coronary syndrome, if we refer to the increased serum level of C-reactive protein, more sensitive than fibrinogen, with increased plasma values in almost half of the patients." (PMID 40278275, 2025). "Several meta-analyses have also confirmed the prognostic value of CRP in acute coronary syndromes." (PMID 41010838, 2025). "Therefore, CRP has been used as a marker of inflammation in various clinical settings of an acute coronary syndrome (ACS)." (PMID 40649166, 2025). "The C‐reactive protein (CRP)‐troponin‐test (CTT) comprises simultaneous serial measurements of CRP and cardiac troponin and might reflect the systemic inflammatory response in patients with acute coronary syndrome." (PMID 38546019, 2024). "In the same study, CRP was found to be higher in patients suffering from acute coronary syndrome." (PMID 38371031, 2024). "Similarly, in patients who recently underwent acute coronary syndrome, a rise of their CRP concertation above 1 mg/L was related to higher rates of HPR (CRP > 1 mg/L vs. ≤1 mg/L: 49.1% vs. 36.4%; p = 0.012)." (PMID 38398278, 2024). "Also, CRP has been found to predict cardiovascular mortality in asymptomatic adults and patients with acute coronary syndrome (ACS)." (PMID 37982862, 2024). "NLR is a better predictor of MACE than CRP in patients with acute coronary syndrome." (PMID 38962087, 2024). "Similar findings were also recently reported among patients with acute coronary syndrome, highlighting the need to explore whether women would derive more benefit from targeted CRP lowering therapies than men." (PMID 37019514, 2023). "Elevated concentrations of C-reactive protein (CRP) early during an acute coronary syndrome (ACS) may reflect the magnitude of the inflammatory response to myocardial damage and are associated with worse outcome." (PMID 35566579, 2022). "Moreover, as the present study indicates, cut-off values for TnI and CRP seem to be higher with regard to myocardial inflammation compared to cut-off values used for diagnosis of acute coronary syndrom." (PMID 33542341, 2021). "Similarly, the Improved Reduction of Outcomes; Vytorin Efficacy International Trial (IMPROVE-IT) randomized 18,144 patients after stabilized acute coronary syndrome to simvastatin and measured CRP and LDL-C." (PMID 32550081, 2020). "C-reactive protein (CRP) is an acute phase protein; several studies have shown that elevated CRP may have prognostic value in patients with acute coronary syndromes who are undergoing percutaneous coronary intervention." (PMID 32466218, 2020). "In addition, one recent study found that a high-sensitivity C-reactive protein (CRP) to the albumin ratio was independently correlated with short-term major adverse cardiac events including CS in patients with acute coronary syndrome (ACS)." (PMID 33294452, 2020). "The prognostic accuracy of the Global Registry of Acute Coronary Events (GRACE) score was improved when combined with three individual biomarkers including hsTnT, NT-proBNP, and high-sensitivity C-reactive protein (hs-CRP) in patients with acute coronary syndrome." (PMID 32016113, 2020). "The study aimed to determine whether high sensitivity C-reactive protein to prealbumin (hs-CRP/PAB) ratio could be used to predict in-hospital major adverse cardiac events (MACE) in patients with acute coronary syndrome (ACS)." (PMID 31399624, 2019). "Similarly, in acute coronary syndrome, miR-21 levels were increased and correlated with CRP, age and visfatin, but negatively correlated with HDL-cholesterol." (PMID 30347712, 2018).
acute coronary syndrome (continued). "In the light of these data, several studies have been performed suggesting that PAPP-A, an inflammatory marker like CRP, may be used in both diagnosis and prognostication of acute coronary syndromes." (PMID 23902711, 2013). "Additionally, evaluation of CRP concentration in patients with acute coronary syndromes provides prognostic information independent from the classical risk factors and enhances the value of well-established risk scores." (PMID 22973074, 2012). "The inclusion of both biomarkers (CRP and BNP) into our analysis might have improved risk prediction as these biomarkers provide additive prognostic information in patients with acute coronary syndromes." (PMID 22973074, 2012). "In this retrospective study, elevated C-reactive protein (CRP) levels measured 24–48 h post-intervention showed a non-significant trend toward association with a higher degree of diastolic dysfunction in patients with acute coronary syndrome (ACS)." (PMID 41303851, 2025). "Altun and colleagues demonstrated that atorvastatin (40 mg/day) treatment in patients with acute coronary syndrome improved the flow-mediated vasodilation, which was accompanied with a decrease in the adhesion molecules E-selectin and sICAM-1 and the inflammatory marker C-reactive protein (CRP)." (PMID 34084561, 2021). "Additionally, CRP and IL-6 are both significantly upregulated in acute coronary syndrome." (PMID 32016113, 2020). "The most tempting hypothesis might be that systemic inflammation largely driven by IL-6 and reflected by elevated CRP stimulates the activation of procoagulant mechanisms, leading to the enhanced thrombin formation, as it was shown in subjects with acute coronary syndrome." (PMID 28429138, 2017). "The predictive value of IL10 was independent of myocardial necrosis but significantly interacted with CRP concentration, suggesting the importance of the balance between pro-inflammatory and anti-inflammatory cytokines as a major determinant of patient’s outcome in acute coronary syndromes." (PMID 23941335, 2013). "This hypothesis was confirmed in presented research through the analysis of the C-reactive protein concentration in plasma, which showed that in patients with acute coronary syndrome the level of CRP was even 100 fold higher than the accepted standards for healthy people." (PMID 22763563, 2012). "In addition, CRP has a strong prognostic value in acute coronary syndromes." (PMID 15456513, 2004). "CRP, albumin, and NLR have been proposed as potential biomarkers for inflammation, particularly in the context of acute coronary syndromes." (PMID 40506944, 2025). "Previous studies have confirmed that IL-1 is a key mediator of the inflammatory response in acute coronary syndrome (ACS), and IL-1 blockade with anakinra significantly inhibited CRP levels (at least partially)." (PMID 40861421, 2025). "The combination of CRP and NLR to predict MACE in patients with acute coronary syndrome was demonstrated to be better than one alone." (PMID 38962087, 2024). "The classical inflammatory marker C reactive protein (CRP) was shown to have independent predictive value in male and female patients with CAD, patients with acute coronary syndrome (ACS) and patients with chronic coronary syndrome (CCS)." (PMID 39759498, 2024). "Other study observed that MHR positively correlates to CRP, Gensini score and SYNTAX score in patients with acute coronary syndrome." (PMID 34330221, 2021). "As the disease progresses, the CRP (C-reactive protein), CD40, and the cardiac myofilament protein troponin can be detected as early indicators of acute coronary syndromes." (PMID 34683334, 2021). "Biomarkers of micro-inflammation, such as C-reactive protein (CRP), serve as predictive tools for the development and monitoring of the acute coronary syndrome, as inflammation is considered a target that can be therapeutically improved." (PMID 32107607, 2020).